KRAS (KRas proto-oncogene, GTPase)
Diseases named in the same sentence as KRAS in open-access papers (continued):
Sharing a sentence is not in itself a finding about the gene and the disease.
pancreatic cancer (continued). "A previous study constructed a LASSO prognostic model based on the m6A regulators and showed that, KRAS mutation status prominently differed between high- and low-risk subgroups in pancreatic cancer." (PMID 34603372, 2021). "Evidence from pancreatic cancer suggests that expression of oncogenic KRAS and loss of SMAD4 cooperate to induce the expression of EGFR and to promote invasion." (PMID 34298611, 2021). "ZNF154 cfDNA methylation discriminated cases from healthy donor plasma samples in minimal plasma volumes and outperformed KRAS mutation frequency in pancreatic cancer." (PMID 33420235, 2021). "Mutations in this gene are associated in with progressive pancreatic cancer in mutant KRAS-induced patients." (PMID 34150632, 2021). "NCT01676259 is investigating siG12D-LODER, a novel biodegradable polymeric matrix containing an siRNA targeting mutated KRAS (KRAS G12X mutation) in advanced pancreatic cancer patients undergoing chemotherapy." (PMID 33804856, 2021). "A TSCS study described the spatial characteristics of metastasis of pancreatic cancer, in which a cutoff of at least 10 CTCs was established as a lower limit for reliable KRAS mutational analysis of CTCs." (PMID 34745998, 2021). "KRAS is the most frequently mutated oncogene in pancreatic cancer, and recent studies have verified that the activation of KRAS in cancer cells affects the properties and functions of the surrounding microenvironment." (PMID 34276760, 2021). "A previously unidentified VTCN1/NRG1 fusion was detected which is a known driver fusion event in pancreatic cancer that lacks KRAS driver mutations." (PMID 34504655, 2021). "Considering that even KRAS mutations—one of the most common oncogenic variants in pancreatic cancer—are hardly detectable with cfDNA in early-stage pancreatic cancer, a low detection rate in our study was inevitable." (PMID 34771630, 2021). "Of note, the mutual exclusivity of mutations was insignificant in pancreatic cancer, except for KRAS and BRAF genes." (PMID 33350171, 2021). "PA4 and PA16 PDX PDAC models were derived from primary human pancreatic tumors that express G12D KRAS, a mutated protein expressed >90% of primary PDAC tumors." (PMID 34298684, 2021). "Despite the high prevalence of KRAS mutations in pancreatic cancer, therapeutic strategies targeting KRAS have thus far been ineffective." (PMID 34944824, 2021). "In pancreatic cancer, the upstream KRAS gene is frequently mutated, which results in the activation of the PI3K/PTEN/AKT/mTORC1 pathway." (PMID 33917370, 2021). "This is characterized to result in an aberrant up-regulation of transcriptional targets like TRA2B (encoding Transformer 2β) in colon cancer or KRAS (encoding Kirsten rat sarcoma viral oncogene homolog) in pancreatic cancer." (PMID 34439945, 2021). "KRAS is a member of the small GTPase superfamily and mutated KRAS is considered a hallmark of pancreatic cancer." (PMID 34863235, 2021). "Mutations in the KRAS gene in pancreatic cancer (PDAC) have caused elevated levels of this branched-chain amino acid." (PMID 34840582, 2021). "KRAS mutation is not limited to pancreatic cancer, and although it is frequently expressed in other malignancies, such as non-small-cell lung carcinoma and colorectal cancer, there are differences in the location of the mutation." (PMID 34829828, 2021).
pancreatic cancer (continued). "The role of aberrant KRAS signaling caused by mutation in pancreatic cancer has been clearly demonstrated in genetically engineered mouse models, with the oncogene KRAS G12D mutation conditionally activated in the embryonic pancreas." (PMID 34046348, 2021). "Genome sequencing analysis has revealed the mutational landscape of pancreatic cancer and KRAS mutations are considered an initiating event in pancreatic ductal cells." (PMID 34590580, 2021). "As mutant KRAS is associated with increased pancreatic cancer cell proliferation and tumor growth, knockdown mutant KRAS expression will result in suppression of PDA cell growth." (PMID 34371702, 2021). "Doxorubicin and Idarrubicin showed also significantly higher activity than the CL0292 and CL0294 compounds when assayed on pancreatic tumor cell lines harboring different KRAS mutations (KRAS G12D in SKPC, PANC1 and HPAF-II, and KRAS Q61H in Hs-776)." (PMID 34439794, 2021). "A hallmark of pancreatic cancer, recalcitrant cancer with a very low survival rate, is the prevalence of oncogenic mutations in the KRAS gene." (PMID 34638560, 2021). "Several exosome proteins, miRNAs and KRAS mutations have been investigated in the hope of carrying out the early detection of pancreatic cancer with high sensitivity and specificity, but they have proven to be insufficient." (PMID 34073722, 2021). "A total of 70 screens were performed in models of KRAS driven cancers including lung, colorectal and pancreatic cancers via CRISPR/Cas9 based loss-of-function screening method." (PMID 34781949, 2021). "Experiments conducted on genetically engineered mouse models have also substantiated the critical role of KRAS mutations in pancreatic cancer initiation and progression 7-10." (PMID 34512171, 2021). "Since activating KRAS mutations can be found as one of the earliest mutations in approximately 90% of pancreatic cancer patients, we started from a state with active KRAS." (PMID 33578795, 2021). "A striking feature of pancreatic cancer is that activating KRAS mutations are found in ∼90% of cases." (PMID 33674596, 2021). "It has been widely acknowledged that KRAS mutation is associated with the poor prognosis of patients with pancreatic cancer." (PMID 34290570, 2021). "Kinugasa and colleagues (2015) analyzed serum KRAS (G12D, G12V and G12R) ctDNA mutations in 75 pancreatic cancer patients, with previously published KRAS mutations in a development cohort, and in 66 patients in an independent blinded validation cohort." (PMID 33673558, 2021). "Cerivastatin, pitavastatin, simvastatin, and fluvastatin also increased the expression of the KRAS gene, the most frequently mutated gene in pancreatic cancer, and frequently mutated in cancer in general." (PMID 34207840, 2021). "This is the first report of the use of second-generation MEK 1 and 2 inhibitor in combination with a chemotherapy agent that has generated a limited increased survival in a small subset of patients with pancreatic cancer with a known KRAS mutation." (PMID 34901697, 2021).
pancreatic cancer (continued). "In fact, alterations in KRAS have been identified in 25% of all cancers, where some cancers like pancreatic cancer contain extremely high mutation rates (90%), while others, such as prostate cancer, show lower mutation rates (7%)." (PMID 33801965, 2021). "On the one hand, more than 90% pancreatic cancer patients carry KRAS mutation, which activates Ras signaling pathway constitutively and promotes pancreatic cancer tumorigenesis and metastasis." (PMID 34348759, 2021). "The dominant nature of activated KRAS mutations causes aggressiveness in pancreatic cancer, and KRAS has a well-established role in cell proliferation, migration, and invasion." (PMID 34202354, 2021). "Second, ddPCR was used to identify potential mutations in BRCA2, EGFR, ERBB2, KDR and KRAS, in a cohort of 188 metastatic pancreatic cancer patients." (PMID 33673558, 2021). "The remaining challenge in this area is the treatment of KRAS mutant cancers, because KRAS is one of the most frequently mutated genes in pancreatic cancer and biliary tract cancer." (PMID 33562094, 2021). "Syndecan-2 also plays a significant role in pancreatic cancer, working as an invasive-associated gene that, as well as syndecan-1, cooperates with KRas to induce the invasive phenotype." (PMID 33669066, 2021). "C-X-C motif chemokine receptor 2 (CXCR2) controls a major inflammatory signaling network in pancreatic cancers with KRAS mutation." (PMID 34638560, 2021). "Selumetinib sulfate is also being tested in patients with locally advanced or metastatic pancreatic cancer harboring KRAS G12R mutations (Clinicaltrials.gov Identifier: NCT03040986 (accessed on 24 February 2021))." (PMID 33801965, 2021). "Mutations in KRAS are almost ubiquitous in pancreatic cancer cells, the importance of which is underscored by the prevalence and severity of murine models of pancreatic cancer driven by mutant KRAS." (PMID 33918004, 2021). "We analyzed survival prediction through the combination of KRAS mutation in cfDNA and CA 19-9 expression in plasma as a representative biomarker of pancreatic cancer." (PMID 34829828, 2021). "Although this looks quite possible, the additional mutations found in GEMMs with the KRAS mutation at tumor onset are known to be unrelated to the mutations found in human pancreatic cancer." (PMID 34745227, 2021). "KRAS mutation occurs in about 90% of pancreatic cancer cases and KRAS drives glycolysis and nucleic acids synthesis." (PMID 34804950, 2021). "Taken together, we have demonstrated that multiscale 3D epigenome reprogramming can promote pancreatic cancer metastasis by activating KRAS-associated pathways, and enhancing adaptive capability to hepatic microenvironment of pancreatic cancer cells." (PMID 34348759, 2021). "Sefrioui and colleagues (2017) used ddPCR in combination with a multiplex assay to screen the seven most common KRAS mutations found in pancreatic cancer." (PMID 33673558, 2021). "The best cell models for studying mitochondrial biology and mitophagy of pancreatic cancer are various human PDAC cell lines with KRAS mutations." (PMID 33718171, 2021). "Blood cancers commonly have NRas and KRas mutations, whereas the majority of solid organ tumors with Ras mutations, including colorectal and pancreatic cancers, generally only have KRas mutations." (PMID 34680208, 2021). "In the present study, we found that HPS is an important mediator that contributes to lipid metabolism in KRAS-mutated pancreatic cancer cells and is involved in cancer cell growth." (PMID 33801246, 2021). "The survival rate of patients with pancreatic cancer with KRAS mutation is worse than that of patients with pancreatic cancer with wild-type KRAS, and is reported to be worse in cases with the G12D mutation than in those with the G12V mutation." (PMID 34829828, 2021).
pancreatic cancer (continued). "Mutated KRAS has a central role in pancreatic cancer development and growth through regulation of T cell cytokines in the microenvironment, therefore shaping the metabolic cancer cell landscape." (PMID 33777798, 2021). "Activating mutations in KRAS are the most frequent genetic events and are present in the majority of pancreatic cancer patients." (PMID 34512171, 2021). "The high prevalence of KRAS mutations (carried by >90% of pancreatic cancer patients) has led to considerable interest in KRAS-targeted therapies." (PMID 34219130, 2021). "Our work suggests that PLEXIND1 functions differently in pancreatic cancer cell lines, and the difference correlates with KRAS mutational status." (PMID 34439202, 2021). "Because KRAS is so frequently mutated and active in cancer, especially in pancreatic cancer, KRAS is often the molecular target of siRNA therapeutics." (PMID 34683931, 2021). "A phase 1 clinical trial (NCT03608631) for treating metastatic pancreatic cancer patients with KRAS G12D mutation with MSC-derived exosomes containing KRAS G12D siRNA (iExosomes) is ongoing." (PMID 34681692, 2021). "Mutations in the oncogenic KRAS gene occur in over 90% of patients and are viewed as driving force of pancreatic cancer." (PMID 33613843, 2021). "Here we show that pancreatic cancer cells that harbor KRAS Q61H mutation exhibit resistance to both catalytic and allosteric SHP2 inhibitors." (PMID 34725361, 2021). "For pancreatic cancer, the oncogenic KRAS mutation is a key driving force for the formation of precursor lesions and subsequent development of PDAC with stromal response." (PMID 33718171, 2021). "KRAS mutations are considered one of the initiating genomic processes in the development of pancreatic cancer, causing permanent activation of RAS pathway leading to carcinogenesis and resistance to systemic treatments." (PMID 35083150, 2021). "We found a link between the most frequently mutated oncogenes in various cancer types, e.g., KRAS mutations in pancreatic cancer and BRAF mutations in skin cancer and the degree to which cancer cells depended on functional versions of these genes for survival." (PMID 33398072, 2021). "Macropinocytosis inhibition with amiloride blocked the growth of KRAS mutated pancreatic cancer xenografts." (PMID 33777798, 2021). "It seems that 95% of late-stage pancreatic cancers present with a mutated and highly overexpressed KRAS." (PMID 33669066, 2021). "Compared with TCGA datasets, the frequencies of KRAS mutations in pancreatic cancer were 56.8% and 56%, respectively." (PMID 34503126, 2021). "Due to the fact that most pancreatic cancers have KRAS mutation, in this study, all of the four PC cell lines have KRAS mutation." (PMID 33692690, 2021). "KRAS is very frequently commonly mutated in pancreatic cancers, the most common type being the PDAC." (PMID 34781949, 2021). "KRAS G12R mutations are the third most common KRAS variant in pancreas cancer after KRAS G12D and G12V mutations and comprise up to 20% of KRAS mutations in some studies." (PMID 33405090, 2021).
pancreatic cancer (continued). "The most commonly known pancreatic cancer-associated oncogene is KRAS, which is activated in most pancreatic tumors." (PMID 34907162, 2021). "First, macropinocytosis has been shown in human pancreatic tumors, a cancer which features a near-universal mutation in KRAS." (PMID 33691728, 2021). "Pancreatic cancer-associated KRAS gene mutations include the missense mutations that result in single amino acid substitutions primarily at codon G12 (98%) with lower frequencies at G13 or Q61." (PMID 33668583, 2021). "A tumor growth promoting role for CXCL2 and CXCL5 was also found in KRAS mutated pancreatic cancer cell lines." (PMID 33777798, 2021). "Based on the results of our study, we believe that the administration of tinzaparin in patients with pancreatic cancer who carry the KRAS mutation is a step towards this direction." (PMID 34208987, 2021). "Other mutations, such as Q61 (<1%) in KRAS exon 3 and K117 and A146 (<1%) in exon 4, seem to be additional hotspots associated with constitutively activated KRAS in pancreatic cancer." (PMID 34638560, 2021). "In analogy to these findings, we had previously observed that pancreatic cancer cells harboring oncogenic KRAS mutations undergo apoptotic cell death upon CUX1 knock-down." (PMID 34070180, 2021). "This would be particularly interesting for cancers like pancreatic cancer that for some cases are caused by a single upregulation of one oncogene (e.g. KRAS)." (PMID 33632214, 2021). "In this study, we tried to determine the KRAS mutation subtype and the extent of the mutation burden in cell-free DNA (cfDNA) as well as in the tumor tissues of patients with pancreatic cancer using ddPCR." (PMID 34829828, 2021). "In colorectal and pancreatic cancer, the presence of mutations in KRAS results in a less responsive tumor when treated with first-generation tyrosine kinase inhibitors like gefitinib." (PMID 33671478, 2021). "For example, in pancreatic cancer, MB 4 and MB 5 contained a higher frequency of KRAS mutations than did the other classes of MBs." (PMID 34930241, 2021). "Several studies on tumor-stromal interactions in pancreatic cancer have suggested that PSCs and KRAS mutations have mutual regulation." (PMID 34540683, 2021). "Resistance to trametinib (MEKs inhibitor) treatment via FGFR1-dependent activation of ERKs and AKT was also observed in lung and pancreatic cancer cells with mutated KRAS." (PMID 34830951, 2021). "KRAS mutation is a major driver mutation in pancreatic cancer and more than 90% of pancreatic cancer patients harbor KRAS mutation." (PMID 34249730, 2021). "In the recent years, KRAS targeting has emerged to be an efficient therapeutic efficacy in context to lung and pancreatic cancer as KRAS mutations are found in 30% of lung and 90% of pancreatic carcinomas." (PMID 34660740, 2021).